ANAPC4 (anaphase promoting complex subunit 4)
Description:
Component of the anaphase promoting complex/cyclosome (APC/C), a cell cycle-regulated E3 ubiquitin ligase that controls progression through the cell cycle. APC/C acts by mediating ubiquitination and subsequent degradation of target proteins: it mainly mediates the formation of 'Lys-11'-linked polyubiquitin chains and, to a lower extent, the formation of 'Lys-48'- and 'Lys-63'-linked polyubiquitin chains. APC/C catalyzes assembly of branched 'Lys-11'-/'Lys-48'-linked branched ubiquitin chains on target proteins. APC/C is activated by CDC20 in the metaphase/anaphase transition of cell cycle, targeting the degradation of cyclin B and securin. APC/C is regulated by the mitotic checkpoint complex (MCC), which inhibits APC/C and delays chromosome segregation.
Synonyms: APC4
Tractability: PROTAC: UniProt records ubiquitination sites on it; ubiquitination databases record sites on it; its protein half-life has been measured.
Gene: Protein-coding gene on chromosome 4 (25,377,210 to 25,420,310, forward strand). Ensembl gene ENSG00000053900.
Subcellular location: Nucleus
Pathways (Reactome):
Cell Cycle: APC-Cdc20 mediated degradation of Nek2A; APC/C:Cdc20 mediated degradation of Cyclin B; APC/C:Cdc20 mediated degradation of Securin; APC/C:Cdc20 mediated degradation of mitotic proteins; APC/C:Cdh1 mediated degradation of Cdc20 and other APC/C:Cdh1 targeted proteins in late mitosis/early G1; Autodegradation of Cdh1 by Cdh1:APC/C; Cdc20:Phospho-APC/C mediated degradation of Cyclin A; Conversion from APC/C:Cdc20 to APC/C:Cdh1 in late anaphase; Inactivation of APC/C via direct inhibition of the APC/C complex; Phosphorylation of the APC/C; Regulation of APC/C activators between G1/S and early anaphase; Separation of Sister Chromatids
DNA Replication: Assembly of the pre-replicative complex; CDK-mediated phosphorylation and removal of Cdc6
Cellular responses to stimuli: Senescence-Associated Secretory Phenotype (SASP)
Disease: Aberrant regulation of mitotic exit in cancer due to RB1 defects
Gene expression (Transcription): Transcriptional Regulation by VENTX
Immune System: Antigen processing: Ubiquitination & Proteasome degradation
Gene Ontology:
Molecular function: protein binding; protein phosphatase binding; ubiquitin-protein transferase activity
Biological process: anaphase-promoting complex-dependent catabolic process; protein branched polyubiquitination; protein K11-linked ubiquitination; protein K48-linked ubiquitination; regulation of meiotic cell cycle; regulation of mitotic cell cycle; protein ubiquitination; regulation of mitotic metaphase/anaphase transition
Cellular component: anaphase-promoting complex; nucleus; cytosol; nuclear periphery; nucleoplasm
Genetic constraint (gnomAD): Loss-of-function variants: 44 observed, 74.73 expected, observed/expected ratio (o/e) 0.59, 90% interval 0.46 to 0.76. The upper end of that interval is the gene's LOEUF score, 0.76, which puts it in group 3 of 6, group 1 being the genes least tolerant of losing a copy. Missense variants: 535 observed, 722.23 expected, observed/expected ratio (o/e) 0.74, 90% interval 0.69 to 0.8. Synonymous variants: 212 observed, 247.7 expected, observed/expected ratio (o/e) 0.86, 90% interval 0.76 to 0.96.
Homologues: Orthologues: chimpanzee ANAPC4 (99% identical), macaque ANAPC4 (99% identical), pig ANAPC4 (98% identical), dog ANAPC4 (98% identical), rabbit ANAPC4 (97% identical), guinea pig ANAPC4 (96% identical), mouse Anapc4 (93% identical), rat Anapc4 (93% identical), tropical clawed frog anapc4 (71% identical), zebrafish anapc4 (62% identical), Drosophila melanogaster APC4 (22% identical).
Diseases named in the same sentence as ANAPC4 in open-access papers:
ANAPC4 is named in the same sentence as 15 diseases in open-access papers, as found by Europe PMC text mining. Sharing a sentence is not in itself a finding about the gene and the disease. The quoted sentences say what the papers report.
COVID-19 (1 paper, 2024). A disease caused by infection with severe acute respiratory syndrome coronavirus 2. "At the transcriptomic level, we found that ANAPC4 emerged as a shared key gene in both COVID-19 and chronic pain." (PMID 38633255, 2024). "Additionally, the gene ANAPC4 was identified as a potential drug target for treating chronic pain (P=7.66E-05) in COVID-19 (P=8.23E-03)." (PMID 38633255, 2024).
esophageal cancer (1 paper, 2024). A primary or metastatic malignant neoplasm involving the esophagus. "ANAPC4 enables esophageal cancer and neural stem cells to proliferate.ANAPC4 transcription and expression are regulated by tRNA methylation and affect cell proliferation." (PMID 38425244, 2024).
glioma (1 paper, 2022). A benign or malignant brain and spinal cord tumor that arises from glial cells (astrocytes, oligodendrocytes, ependymal cells). "Moreover, analysis of genes and proteins that interact with KIF18A showed that several molecules related to cell cycle and cell division, such as RRP7A, ANAPC4, WEE1, CDC20, and NDC80, were enriched in glioma." (PMID 35591854, 2022).
systemic lupus erythematosus (1 paper, 2021). An autoimmune multi-organ disease typically associated with vasculopathy and autoantibody production. "Module 2 contained 6 DEGs (ANAPC4, HIST2H2BD, HIST2H2BE, etc.), and these genes were mainly enriched in 7 GO terms and 4 KEGG pathways, such as nucleosome assembly (GO: 0006334), protein-DNA complex assembly (GO: 0065004), and pathways like systemic lupus erythematosus pathology (hsa05016)." (PMID 34116668, 2021).
triple-negative breast carcinoma (1 paper, 2024). An invasive breast carcinoma which is negative for expression of estrogen receptor (ER), progesterone receptor (PR), and human epidermal growth factor receptor 2 (HER2). "ANAPC4 inactivation confers resistance to multiple TTK protein kinase inhibitors in triple-negative breast cancer." (PMID 38425244, 2024).
cancer (4 papers, 2016 to 2024). A tumor composed of atypical neoplastic, often pleomorphic cells that invade other tissues. "Subsequent analyses confirm that both TRMT13 and ANAPC4 expressions are downregulated in PTC tissues and that this change in expression has a significant impact on cancer diagnosis." (PMID 38425244, 2024). "Compared with those in the control group, cancer cell migration and invasion were lower in the TRMT13+/+ and ANAPC4+/+ groups but greater in the TRMT13 siRNA and ANAPC4 siRNA groups." (PMID 38425244, 2024). "These include the tumour suppressors, PDCD4, RB1, STK2, transcriptional regulators with reported roles in cancer, BCL9L, STAT5B and proteins that are involved in control of the cell cycle, ANAPC4, ANAPC5, RBX1." (PMID 35573784, 2022). "The role of ANAPC4 in cancer has not been studied in detail." (PMID 32899298, 2020). "RPS6KA1, WFS1, ANAPC4 and TUBB4A have not been investigated in EC prior to this, and further studies are indicated to elucidate how these genes may affect survival in cancer in general, as well as their role in EC." (PMID 32899298, 2020).
tumor (3 papers, 2022 to 2024). "ANAPC4 abnormalities promote proliferation and correlate with tumor diameter in oral squamous cell carcinoma." (PMID 38425244, 2024). "In the nude mouse xenograft model, both TRMT13 and ANAPC4 inhibit tumor growth, and TRMT13 and ANAPC4 expression levels are significantly associated with survival." (PMID 38425244, 2024). "The relative TRMT13 and ANAPC4 expression levels in the tumor tissue are shown inFigure 8D,E." (PMID 38425244, 2024). "However,ANAPC4 overexpression significantly reduced tumor volume, whereasANAPC4 silencing significantly promoted tumor growth and reduced survival." (PMID 38425244, 2024). "Tumor volume and mass were greater in the TRMT13+/++ANAPC4 siRNA group than in the TRMT13+/+ group and lower in the TRMT13 siRNA+ANAPC4+/+ group than in the TRMT13 siRNA group." (PMID 38425244, 2024). "Subgroup U-II was more related to tumor proliferation, including cell cycle (MCM2, ANAPC4, CHEK1, etc.), RNA splicing, and DNA repair." (PMID 35659036, 2022). "A nude mouse tumor model is used to evaluate the effects of TRMT13 and ANAPC4 on PTC tumorigenesis." (PMID 38425244, 2024).
infection (2 papers, 2024 to 2026). The state of being infected such as from the introduction of a foreign agent such as serum, vaccine, antigenic substance or organism. "We next determined the time course of APC4 loss upon Cre-infection in ANAPC4 cKO cortical neurons." (PMID 38932933, 2024).
ANAPC4 also shares sentences with these, for which no sentence is quoted: asthma (1 paper); carcinosarcoma (1); depression (1); insomnia (1); papillary thyroid cancer (1); psychiatric disorder (1); schizophrenia (1).